KMT5A (lysine methyltransferase 5A)
Diseases named in the same sentence as KMT5A in open-access papers:
KMT5A is named in the same sentence as 79 diseases in open-access papers, as found by Europe PMC text mining. Sharing a sentence is not in itself a finding about the gene and the disease. The quoted sentences say what the papers report.
breast carcinoma (19 papers, 2010 to 2024). "In addition, loss of KMT5A catalytic activity by KMT5A depletion or KMT5A-selective inhibitor combined with YAP signaling inhibition impedes breast cancer progression using a mouse xenograft model of breast cancer metastasis." (PMID 35449131, 2022). "Strikingly, combined treatment of verteporfin with KMT5A depletion was more effective than that of single-agent treatment in both breast cancer cell lines invasion." (PMID 35449131, 2022). "Here, we identify that SNIP1 is a non-histone substrate of lysine methyltransferase KMT5A, which undergoes KMT5A-mediated mono-methylation to promote breast cancer cell growth, invasion and lung metastasis." (PMID 35449131, 2022). "Considering the critical role of the Hippo/YAP signaling pathway in KMT5A/SNIP1/MARK4-driven breast cancer progression and metastasis, the effects of verteporfin treatment combined with KMT5A-depletion on breast cancer metastasis were assessed." (PMID 35449131, 2022). "In addition, unlike the normal breast epithelium cell line MCF-10A cells, KMT5A expression was significantly higher in all breast cancer cells." (PMID 35449131, 2022). "Moreover, loss of KMT5A catalytic activity by KMT5A depletion or KMT5A-selective inhibitor, and combined with YAP signaling inhibition significantly impairs breast cancer progression and metastasis." (PMID 35449131, 2022). "Co-inhibition of KMT5A catalytic activity and YAP in TNBC xenograft-bearing animals attenuates breast cancer metastasis and increases survival." (PMID 35449131, 2022). "And our results identified UNC0379, a KMT5A selective inhibitor, cooperates with YAP signaling inhibition to prevent breast cancer progression and metastasis, which may help overcome the narrow therapeutic index of single treatment strategy." (PMID 35449131, 2022). "Furthermore, the metastatic breast cancer cell lines (4T1, BT549, and MDA-MB-231) expressed higher levels of KMT5A than those of non-metastatic breast cancer cell lines (MDA-MB-453, MCF7, T47D, and BT474)." (PMID 35449131, 2022).
hepatocellular carcinoma (18 papers, 2013 to 2026). A malignant tumor that arises from hepatocytes. "For functional analyses, we conducted a loss-of-function study of SETD8/KMT5A using hepatocellular carcinoma cell lines, including in vitro assays for proliferation, cell cycle, invasion, and RNA sequencing with gene ontology analysis." (PMID 41973766, 2026). "KMT5A facilitates hepatocellular carcinoma growth by enhancing aerobic glycolysis." (PMID 35449131, 2022).
Hyperglycemia (12 papers, 2020 to 2024). An increased concentration of glucose in the blood. "The levels of H4K20me1, a downstream target of KMT5A, decreased in hyperglycemia-treated HUVECs and the levels of H4K20me1 were enriched in the promoter region of enolase 1 (ENO1), regulating the ENO1 levels and thereby inducing EndMT." (PMID 36983082, 2023). "In conclusion, CREB associates with KMT5A to promote PTP1B expression in vascular endothelial cells, thus contributing to hyperglycemia-induced inflammatory factor levels in DN patients and rats." (PMID 33782381, 2021). "KMT5A associated with RFX1 to modulate ENO1, thus involved in hyperglycemia-mediated EndMT in glomeruli of DN." (PMID 34803485, 2021). "Our previous research illustrated KMT5A is involved in hyperglycemia-induced endothelial damage 19-23." (PMID 34803485, 2021). "However, the underlying mechanism by which KMT5A participates in hyperglycemia-mediated EndMT is still not well studied." (PMID 34803485, 2021). "The present study indicated that ets1 cooperated with KMT5A to transcribe PFN2, thus contributing to hyperglycemia-induced EndMT in the glomerular endothelial cells of DN patients and rats." (PMID 34238215, 2021). "In the present study, we speculated KMT5A regulates ENO1 transcript, thus participating in hyperglycemia-induced EndMT in glomeruli of DN." (PMID 34803485, 2021). "In this study, we speculate that KMT5A may regulate ENO1 levels, thus participating in hyperglycemia-induced EndMT in vascular endothelium." (PMID 34803485, 2021).
non-small cell lung carcinoma (9 papers, 2013 to 2024). A group of at least three distinct histological types of lung cancer, including non-small cell squamous cell carcinoma, adenocarcinoma, and large cell carcinoma. "The glycoprotein CD147 is dimethylated to CD147-K234me2 by lysine methyltransferase 5A (KMT5A); overexpression of CD147-K234me2 and KMT5A enhances glycolysis and lactate export in non-small cell lung cancer (NSCLC) cells." (PMID 39062577, 2024).
osteosarcoma (5 papers, 2016 to 2023). A usually aggressive malignant bone-forming mesenchymal neoplasm, predominantly affecting adolescents and young adults. "The inhibitory importance of KMT5A in the proliferation and metastasis of osteosarcoma cells through the transmission of β-catenin signals is also known." (PMID 36836762, 2023).
prostate carcinoma (4 papers, 2020 to 2023). A carcinoma that arises from epithelial cells of the prostate gland. "The methyltransferase KMT5A is suggested as an oncogene in prostate cancer but the mechanisms underlying its oncogenic properties are poorly understood." (PMID 37509260, 2023). "KMT5A has been proposed as a therapeutic target in prostate cancer; however, in this context, KMT5A is still largely understudied." (PMID 37509260, 2023). "The protein methyltransferase KMT5A has been shown to interact with the androgen receptor and was proposed to offer therapeutic benefits to prostate cancer patients." (PMID 37509260, 2023). "The methyltransferase KMT5A has been proposed as an oncogene in prostate cancer and therefore represents a putative therapeutic target." (PMID 37509260, 2023). "A positive correlation between KMT5A and CDC20 expression was also observed in clinical prostate cancer samples, further supporting this association." (PMID 37509260, 2023). "In order to confirm that the methyltransferase activity of KMT5A is important for the regulation of CDC20 expression in prostate cancer cell lines we used two molecules that have shown inhibitory activity against KMT5A, namely UNC0379 and Ryuvidine." (PMID 37509260, 2023). "Taken together, the cellular processes and genes altered in this analysis further support our hypothesis that KMT5A is a potential therapeutic target for prostate cancer." (PMID 37509260, 2023). "However, the mechanisms by which KMT5A contributes to prostate cancer progression remains poorly understood." (PMID 37509260, 2023). "With inhibitors for both CDC20 and KMT5A being developed, it would be important to determine whether or not they are able to synergise with each other in drug-resistant models of prostate cancer." (PMID 37509260, 2023). "Furthermore, two articles describe CDH1 repression in prostate cancer by ZEB1 binding either to NAD-dependent protein deacetylase sirtuin-1 (SIRT1) or to lysine methyltransferase 5A (SET8)." (PMID 32796736, 2020). "Therefore, we conclude that KMT5A is a valid therapeutic target for the treatment of prostate cancer and CDC20 could potentially be utilised as a biomarker for effective therapeutic targeting." (PMID 37509260, 2023). "This relationship between CDC20 and KMT5A is supported by a significant positive correlation between KMT5A and CDC20 transcripts in prostate cancer patients." (PMID 37509260, 2023). "Taken together, this suggests that the positive correlation between KMT5A and CDC20 observed in our cell line models is also observed in advanced prostate cancer." (PMID 37509260, 2023). "To confirm whether or not our in vitro findings could be translated into clinical specimens of prostate cancer, we interrogated publicly available datasets to confirm a positive correlation between CDC20 and KMT5A transcripts." (PMID 37509260, 2023). "Furthermore, we demonstrate that KMT5A and CDC20 are positively correlated in clinical samples of prostate cancer." (PMID 37509260, 2023). "A greater understanding of KMT5A in the context of prostate cancer is required to determine whether or not it is a bona fide therapeutic target." (PMID 37509260, 2023). "This study uncovers genes and cellular pathways which are regulated by KMT5A in prostate cancer to obtain a better understanding of whether or not therapeutic targeting is viable." (PMID 37509260, 2023). "Indeed, no study has identified which genes KMT5A can regulate in castration-resistant prostate cancer." (PMID 37509260, 2023). "Furthermore, KMT5A plays a role in the epithelial–mesenchymal transition (EMT) and enhances the invasiveness of prostate cancer cell line models, independent of the AR through its interplay with ZEB1." (PMID 37509260, 2023).
colorectal cancer (3 papers, 2020 to 2024). A primary or metastatic malignant neoplasm that affects the colon or rectum. "Additionally, a polymorphism (rs 16917496) at the miR-502 binding site of the lysine methyltransferase 5A (SET8) and its correlation with colorectal cancer have been reported in a GWAS study on SETD8 and cancer." (PMID 33339442, 2020).
autism (1 paper, 2023). Persistent deficits in social interaction and communication and interaction as well as a markedly restricted repertoire of activity and interest as well as repetitive patterns of behavior. "While KMT5A represents a novel gene, KMT2C, also known as MLL3, is a well-established gene linked to intellectual disability and autism." (PMID 38025430, 2023).
colon adenocarcinoma (1 paper, 2023). "In stomach adenocarcinoma (STAD), lung adenocarcinoma (LUAD), and colon adenocarcinoma (COAD), STAG2‐mutant tumors exhibited a trend of high KMT5A expression compared with STAG2WT tumors." (PMID 37985839, 2023).
oesophageal cancer (1 paper, 2020). "Furthermore, KMT5A/SET8 knockdown suppressed the proliferative, migratory and invasive capacities of cancer cells in vitro, as well as tumour development in vivo and promoted apoptosis of oesophageal cancer cells." (PMID 32429269, 2020).
parathyroid adenomas (1 paper, 2019). "Among those genes up-regulated in parathyroid adenomas, some, such as MED12, KMT5A, BMP2K, and ATAD2, are implicated in cell proliferation and transcriptional regulation, supporting the notion that they potentially contribute to tumorigenesis." (PMID 30832348, 2019). "Therefore, KMT5A should be further validated as a possible biomarker for parathyroid adenoma progression or development." (PMID 30832348, 2019).
prostate neuroendocrine carcinoma (1 paper, 2023). "Interestingly, the highest positive correlation between CDC20 and KMT5A expression was seen in prostate neuroendocrine carcinoma samples (Spearman = 0.68; p < 0.0001; n = 49)." (PMID 37509260, 2023).
uterine corpus endometrial carcinoma (1 paper, 2023). A endometrial carcinoma (disease) that involves the body of uterus. "Among the tumor types with a high frequency of STAG2 mutation, STAG2‐mutant uterine corpus endometrial carcinomas (UCEC) showed a significant increase in KMT5A expression compared to STAG2‐proficient UCECs." (PMID 37985839, 2023).
cancer (59 papers, 2013 to 2026). A tumor composed of atypical neoplastic, often pleomorphic cells that invade other tissues. "Epigenetic regulators are known to play a critical role in cancer progression, and the histone methyltransferase SETD8/KMT5A has been reported to be overexpressed in various malignancies." (PMID 41973766, 2026). "SETD8, known as KMT5A or SET8, specifically targets H4K20 for methylation and has been implicated in multiple cancer processes." (PMID 30002791, 2018). "The lysine methyltransferase, KMT5A, plays an oncogenic role in a number of cancers." (PMID 37509260, 2023). "As both CDC20 and KMT5A are up-regulated in cancer via a number of mechanisms, the relationship between the two proteins may be dysregulated, thereby promoting genomic instability." (PMID 37509260, 2023). "RSG could also be a new inhibitor of KMT5A protein, whose inhibition could lead to the dysregulation of protein methylation, which is directly connected with neurodegenerative diseases and cancer." (PMID 33670968, 2021). "Overall, after studying acrylamide, 2-acetylaminofluorene, 1,3-butadiene, furan, and methapyrilene, and examining cancer-target and non-cancer-target tissues for adducts and epigenetic effects, only abundance of H4K20me3 and KMT5A/B/C could identify the cancer-target tissue." (PMID 34681626, 2021). "Importantly, this study reveals that KMT5A-mediated SNIP1 K301 methylation not only serves as a key signal driving c-MYC hyper-activation and cancer metastasis, but also acts as a marker of poor prognosis of TNBC patients." (PMID 35449131, 2022).
tumor (56 papers, 2013 to 2026). "The instability of KMT5A in these individuals may also make them more susceptible to tumorous diseases, warranting attention to preventive measures and monitoring." (PMID 40225938, 2024). "In NSCLC, CD147-K234me2—a di-methylated variant of CD147 at Lys-234 catalyzed by lysine methyltransferase 5A (KMT5A)—enhances glycolytic flux and lactate export, thereby promoting tumor progression." (PMID 41479915, 2025). "Consistent with the results in vitro, STAG2KO tumor lysates exhibited increased expression of KMT5A and H4K20me1 protein, but a marked reduction of H4K20me0 expression." (PMID 37985839, 2023). "Taken together, these results demonstrate that KMT5A-dependent SNIP1 methylation promotes TNBC tumor and lung metastasis by activating MARK4 transcription and subsequent modification of the Hippo/YAP signaling pathway." (PMID 35449131, 2022). "As a result, KMT5A was more highly expressed in matched metastatic lymph nodes than in the primary tumor." (PMID 35449131, 2022). "The results showed that overexpression of LINC00473 significantly promoted tumor growth, and the xenograft tumors had the larger volume and the higher Ki-67 and KMT5A positive rate." (PMID 34091587, 2021). "Cytotoxic molecules (i.e., granzyme B, perforin) was also increased in miR-340-5p-overexpressing tumor cells and significantly reversed by KMT5A-OE." (PMID 33168024, 2020). "miR-340-5p inhibition significantly promoted tumor cell viability, and KMT5A knockdown or APCP significantly reversed this impact." (PMID 33168024, 2020). "It has tumor suppressor effect via inhibiting proliferation by targeting KMT5a (Histone-Lysine N-Methyltransferase KMT5A) and ITGA6 (Integrin, Alpha 6)." (PMID 30945144, 2019). "Then, an LDH assay was performed, and the negative control DLBCL cells triggered a relatively stronger cytotoxicity in an E:T ratio-dependent manner, while T cells cocultured with KMT5A-overexpressing DLBCL cells displayed a relatively lower capacity for tumor cell lysis." (PMID 33168024, 2020). "To further identify the correlation of KMT5A and CD8+ T-TILs, we next used 30 tumor samples from DLBCL patients collected at diagnosis." (PMID 33168024, 2020). "In line with these in vitro findings, ectopic of SNIP1K301M, but not SNIP1WT, restored KMT5A depletion-mediated inhibition of proliferation and invasion in vitro, as well as tumor growth and lung metastasis in vivo, and decreased KMT5A depletion prolonged animal survival." (PMID 35449131, 2022). "Considering that CD8+ T-cell functional avidity was demonstrated to be related to superior control of tumor growth, we then cultured CMV peptide pool-stimulated CD8+ T cells with KMT5A-overexpressing or negative control LY-1 cells." (PMID 33168024, 2020).
inflammation (3 papers, 2020 to 2022). Aberrant reaction of the microcirculation characterized by movement of fluid and leukocytes from the blood into extravascular tissues. "In the present study, we hypothesise that CREB associates with KMT5A to modulate PTP1B expression, thus contributing to high glucose-mediated glomerular endothelial inflammation." (PMID 33782381, 2021).
KMT5A also shares sentences with these, for which no sentence is quoted: ovarian carcinoma (9 papers); bladder cancer (7); neuroblastoma (7); pancreatic cancer (7); cervical cancer (6); diabetic nephropathy (6); lung carcinoma (5); small cell lung carcinoma (5); diabetes (4); gastric cancer (4); glioma (4); melanoma (4); multiple myeloma (4); Obesity (4); acute myeloid leukemia (3); chronic myelogenous leukemia (3); infection (3); papillary thyroid cancer (3); acute kidney injury (2); acute lymphoblastic leukemia (2); clear cell renal cell carcinoma (2); colon cancer (2); endometrial cancer (2); esophageal cancer (2); liver cancer (2); lymph node metastasis (2); non-Hodgkin lymphoma (2); renal carcinoma (2); triple-negative breast carcinoma (2); anemia (1).
A further 33 diseases each share a sentence with KMT5A in 1 paper.